ESR1 (estrogen receptor 1)
Diseases named in the same sentence as ESR1 in open-access papers (continued):
Sharing a sentence is not in itself a finding about the gene and the disease.
breast cancer (continued). "For ESR1 mutation patients, significant PFS improvement is observed with Camizestrant and Elacestrant monotherapy, which have been recommended in multiple guidelines and could become the new cornerstone of endocrine therapy for HR + /HER2 − breast cancer patients." (PMID 38212842, 2024). "Preclinical mouse models of breast cancer studies (xenograft and PDX) showed that elacestrant prevents E2-induced tumor growth in ESR1 WT and mutants." (PMID 39767607, 2024). "The detection of ESR1 mutations through serial ctDNA monitoring is a hot topic now in the clinical field, since it allows for the quantitative assessment of changes in its allele frequency among patients who have advanced HR+ ​breast cancer as frontline treatment." (PMID 40027941, 2024). "Immunohistochemical data from the HPA database supported these findings, showing elevated PIK3R1, ESR1, and AKR1C3 levels in breast cancer tissues, aligning with their proposed roles in cancer cell proliferation and hormone regulation." (PMID 39204124, 2024). "Our findings revealed distinct coexpression patterns of MET/ESR1 and MET/ESR2, each correlating with specific clinicopathologic features and clinical outcomes, thereby enriching the prognostic landscape of breast cancer." (PMID 39742369, 2024). "In detail, TFAP2C upregulates ER-related genes (ESR1, FOXA1 and GATA3) to maintain the phenotypes of luminal breast cancer." (PMID 37291585, 2023). "Collectively, our findings contribute to the growing body of evidence supporting a correlation between ESR1 and HOTAIR in breast cancer pathogenesis." (PMID 38114755, 2023). "Two single nucleotide variants (SNV; SNP) located in a distal enhancer region 5′ to the human estrogen receptor 1 (ESR1) gene (rs2046210 and rs9383590) were genotyped in a hospital-based case-control study of 409 breast cancer patients and 422 female controls." (PMID 36831182, 2023). "The Supertarget genes, FOXA1, ESR1, and GATA3, are among the most studied prognostic markers and therapeutic targets in breast cancer." (PMID 37297004, 2023). "Among the several miRNA–mRNA target interactions in TNBC and/or breast cancer in general, the cancer driver genes, such as BRCA1, ESR1, PTEN, and AKT1, were observed." (PMID 37685851, 2023). "In this study, we demonstrate a significant correlation between the expression levels of ESR1, HOTAIR, and miR-130a in the serum of breast cancer patients." (PMID 38114755, 2023). "The TCGA data showed that young-age breast cancer patients have a lower level of expression of RANBP3L, GLYATL-1, and ESR1, whereas ACVR2A, SERPINE2, and PCDHGB7 have higher expression in young-age breast cancer patients compared to old age patients." (PMID 36672708, 2023). "For some known genes related to breast cancer (e.g., MYC, IGFBP5, CCND1, ESR1), we confirmed epithelial cells showed higher expression levels." (PMID 37340002, 2023). "On the one hand, breast cancers evolved resistance mechanisms, such as RB1 inactivation or ESR1 gain-of-function changes, to deregulate cell cycle control and drive aggressive cell growth and proliferation." (PMID 37475004, 2023). "Reduction in the levels of ESR1 via the DSCAM-AS1/miR-130a axis also correlates with a decrease in the cancerous properties of cells, impeding breast cancer cell invasion and migration, similar to progesterone treatment." (PMID 37395734, 2023). "In this study, the expression of ESR1 mRNA in formalin-fixed, paraffin-embedded (FFPE) canine mammary tumors (CMTs) was evaluated and compared with the expression levels of miR18a and miR18b, both assessed via RT-qPCR." (PMID 36978627, 2023). "As an example, our results showed enrichment of RUNX1, ESR1, FOXA1, and FOXM1 target genes in breast cancer type-specific GRNs." (PMID 37627195, 2023).
breast cancer (continued). "In breast cancer, most oncogenic alterations were enriched in TMB and bTMB≥10 samples, with the notable exception of ESR1, consistent with hormone-receptor positive breast cancer having lower TMB than other subtypes." (PMID 40027285, 2023). "Via analysis of transcriptome data of breast cancer, FBXW9 was related to the activities of several cell cycle regulators including MYC and ESR1." (PMID 36982338, 2023). "Estrogen receptor alpha (ESR1) and its ligand estradiol (ESR2) is critical for growth of about 70 % of breast cancers." (PMID 38034788, 2023). "For example, GATA3, ESR1, and TRPS1 were identified as the three leading master regulators in breast cancer." (PMID 37600846, 2023). "Given the observed difference with breast cancer tumor subtypes, we investigated DNAm AA with respect to gene expression levels of ESR1 (estrogen receptor 1) and PGR (progesterone receptor) in these women." (PMID 36991516, 2023). "The regulation of DSCAM-AS1 expression by ER and PR in breast cancer cells in response to progesterone suggests a potential feed-forward mechanism between DSCAM-AS1 and ESR1 in breast cancer." (PMID 37395734, 2023). "In this study, we identified CA12 as one of the ERα target genes whose RNA expression is most correlated with that of ESR1, GATA3 and FOXA1 in breast cancer datasets." (PMID 36358871, 2022). "Antiestrogens with improved potencies including bazedoxifene, fulvestrant, OP-1074 and GDC-0945 possess variable degrees of ERα degrading/downregulating activities but show significant potencies and efficacies in mutant ESR1 breast cancer cells." (PMID 35575456, 2022). "The Luminal B2 subtype of HER2-positive breast cancer, which overexpressed GATA3, BCL2, and ESR1 genes, was found to account for roughly half of all HER2-positive breast cancer subtypes." (PMID 36034650, 2022). "Lastly, ESR2 (ERβ gene) expression was negatively correlated with ESR1 (ERα gene) and CCND1 RNA expression in human metastatic ERα+/HER2- breast cancer samples." (PMID 35574319, 2022). "Intriguingly, ERα-LBD expression and function does not appear to be restricted to cancers that express full length ERα but also promotes growth of triple-negative breast cancers and ERα-LBD transcript (ESR1-LBD) is also present in BC samples from both ERα(+) and ERα(−) human tumors." (PMID 35999225, 2022). "The presence of the ESR1 fusions with AKAP12, ARMT1 and CCDC170 (exon 2 to exon 11) was evaluated in breast cancer tissue samples from 732 breast cancer patients." (PMID 35151276, 2022). "We analyzed a total of 6 genes: ESR1, DRD2, LINE1, MST1R, that we have previously demonstrated to be differentially methylated in prostate and breast cancers." (PMID 36067197, 2022). "We measured the expression levels of ESR1 and ESR2 genes in immortalized mammary epithelial cells and different breast cancer cell lines." (PMID 35574319, 2022). "SMAD3 BMPR2, XIAP, and ESR1 have also been proven to be regulated by OS in skin fibroblasts, vascular smooth-muscle cells, PC6.3 cells, and breast cancer." (PMID 35954205, 2022). "It is noteworthy that up to date, only few ESR1 fusions (ESR1-e2>CCDC170, ESR1-e4>CCDC170, ESR1-e5>CCDC170, ESR1-e6>NOP2, ESR1-e6>AKR1D1, ESR1-e6>POLH) were detected in primary breast cancer samples." (PMID 36686845, 2022). "We developed LATS inhibitors that effectively suppress the expression of ESR1 and revealed a proof of concept that LATS is potential therapeutic target for ER+ breast cancer, particularly those with hormone therapy resistant ESR1 mutations." (PMID 35217640, 2022). "In breast cancer, for example, the PADA1 study addressed this specific question using ESR1 as a candidate biomarker." (PMID 35955679, 2022).
breast cancer (continued). "The results were further filtered against a list of all genes in two systems biology models of breast cancer: one involving RAS signalling and the other ESR1 signalling." (PMID 35382578, 2022). "Albeit rare, an ERBB2 fusion identified in a patient with HER2+ breast cancer and an acquired RET fusion identified in a patient with an acquired ESR1, offer interesting insights into subtype-specific resistance mechanisms and warrant further investigation." (PMID 36470901, 2022). "In this work, we investigated ERα protein and transcripts in ESR1 wild-type breast cancers that were resistant to fulvestrant and in TNBC." (PMID 35999225, 2022). "Both EC cell lines showed low expression of ESR1 and ESR2 as compared to the T47D breast cancer line used as a positive control." (PMID 36727068, 2022). "Thus research suggests that anti-estrogen resistant breast tumors with ESR1 amplification, identified in almost 20% of metastatic ER+ breast cancers, as well as decreased levels of protein-folding chaperones, may be targeted by estrogen (17β-estradiol) treatment." (PMID 35053443, 2022). "To further verify that these genes were regulated by these three TFs, we analyzed gene-expression data from knockdown (FOXA1 and ESR1) and over-expression (GATA3) experiments in breast cancer cell lines (see “Methods” section)." (PMID 34518541, 2021). "Specifically, TOM1L1 and ESR1 were highly expressed, but MAFF, TNS1, EFEMP2, and TRIM31 were significantly downregulated in breast cancer." (PMID 34151731, 2021). "Like ESR1, PIK3CA is a promising predictive biomarker for HR+ breast cancer in patients treated with targeted therapy for the PI3K pathway." (PMID 33692409, 2021). "Methylation at many gene promoters has been reported to have independent prognostic value in breast cancer including HOXA11, ESR1 and PITX2, HOXD13 CDH22 BRCA1 and RASSF1." (PMID 33461604, 2021). "However, the mechanism and biological function of ESR1 SUMOylation in breast cancer remain unclear." (PMID 34508066, 2021). "In breast cancer, LINC01116 directly combines with miR-145 to increase ESR1 expression, and subsequently promotes tumor development." (PMID 33762953, 2021). "Various strategies that target mutant ESR1 breast cancer, including novel estrogen receptor down regulator (SERD) or estrogen receptor modulator (SERM) orally bioavailable, are in clinical development." (PMID 34771560, 2021). "Given the prevalence of ESR1-MUT, its intrinsic link with the processes driving HR-positive breast cancer, and its large impact on outcomes of a variety of therapies, ongoing trials should stratify patients by ESR1-MUT status." (PMID 34392831, 2021). "ESR1 was also co-expressed with known marker genes, including known ERGs, cancer-related genes from CGC, ER-DEGs, and breast cancer-related genes from GAD." (PMID 33987091, 2021). "These similarities indicate that subtyping of MIBC tumours based on mRNA analysis of ERBB2 and ESR1 expression has a clinical value in the prediction of pCR following NAC, as it is observed for breast cancer patients." (PMID 34073233, 2021). "Collectively, these results support the view that TRIM3 upregulation promotes ESR1 SUMO modification and ER signaling pathway activity, leading to tamoxifen resistance in ER+ breast cancer." (PMID 34508066, 2021).
breast cancer (continued). "The Xpert® Breast Cancer STRAT4* Assay (STRAT4)*, a standardized test for ESR1/PGR/MKi67/ERBB2 mRNA biomarker assessment, takes less than 2 hours." (PMID 33879115, 2021). "The second study reported high inter-site and intra-site reproducibility of ESR1, PGR, ERBB2, and MKi67 mRNA measurements with the MammaTyper® test and showed a precise and reproducible assessment of the four breast cancer biomarkers." (PMID 34371382, 2021). "The estrogen receptor signaling is mediated by estrogen receptors, ESR1 and ESR2, while the majority of breast cancers have disregulated estrogen receptor signaling." (PMID 34055017, 2021). "In breast cancer, HOXB5 enhanced cell growth and invasion partly through RET, ERBB2, EGFR, and ESR1." (PMID 34440097, 2021). "The high expression of LINC01235 leads not only to ESR1 imbalance and drug resistance, but also to abnormal expression of ADRA2A, leading to the deterioration of breast cancer." (PMID 34490040, 2021). "All patient-specific subnetworks contained relevant drug targets that have been largely studied in breast cancer (e.g., ERBB2, ESR1, EGFR, AKT1)." (PMID 33706810, 2021). "The most important TFs for breast cancer, such as FOXA1 and ESR1, are among the most significant results from the mixed model but less evident in the results from the LD score regression." (PMID 34518541, 2021). "Consistent with this, in preclinical work, endocrine-resistant and ESR1-MUT breast cancer cells retain palbociclib sensitivity, and PDX models with ESR1-MUT also remain sensitive to palbociclib and abemaciclib." (PMID 34392831, 2021). "Taken together, our results revealed the crucial role of TRIM3 in SUMOylation of ESR1 and the modulation of the tamoxifen response, identifying TRIM3 as a potential target to improve clinical outcomes of breast cancer." (PMID 34508066, 2021). "We then examined PROCR (a known breast cancer stem cell marker) expression in MDA-MB-231 cells and ESR1 expression in ZR-75-1 cells upon baicalin treatment." (PMID 34295892, 2021). "The present study showed that targets of Chrysanthemum phytochemicals (luteolin, chlorogenic acid, rutin, quercetin, and apigenin) belong to estrogen receptors such as ESR1, ESR2, and PGR and are major therapeutic targets of breast cancer." (PMID 34083561, 2021). "Accordingly, previous studies have demonstrated that drugs targeting ESR1, ESR2, and PGR are effective in the treatment of breast cancer and improve promote clinical outcomes." (PMID 34322374, 2021). "ESR1 is positively correlated with DNAJC12 and ERBB4, and DNAJC12 is positively correlated with ERBB4 in breast carcinoma." (PMID 33718139, 2021). "The cBioPortal tool was employed to analyze the TCGA database for correlativity among the expression of ESR1, DNAJC12, and ERBB4 in breast carcinoma." (PMID 33718139, 2021). "In summary, we have determined that ESR1 and ERBB4 are upstream and downstream genes, respectively, of DNAJC12 in breast carcinoma." (PMID 33718139, 2021). "Currently, DNAJC12 has been seldom researched in breast carcinoma, and the relation between DNAJC12 and ESR1 is still unclear." (PMID 33718139, 2021).
breast cancer (continued). "ESR1 positively correlates with DNAJC12 and ERBB4, and DNAJC12 also positively correlates with ERBB4 in breast carcinoma." (PMID 33718139, 2021). "For example, the presence of genomic alterations in genes such as ERBB2, PIK3CA, AKT1, ESR1 and NTRK in advanced breast cancer patients help to stratify patients for targeted therapies." (PMID 33167363, 2020). "In order to explore the ESR1-mediated miRNA-mRNA molecular regulatory mechanism in ERα positive breast cancer, dataset GSE38280 containing 4 luminal A and 4 luminal B breast cancer samples was selected in this study." (PMID 32500028, 2020). "For HER2, ESR1, and PGR analysis, we were able to identify 102 breast cancer samples with matched transcriptomic and proteomic profiles." (PMID 32397474, 2020). "A trend of an increasing number of driver alterations of breast cancer-related genes was observed in recurrence samples as compared to primary tumors, including alterations in FGFR1, ESR1, NF1, BRCA1, and PTEN genes." (PMID 33059724, 2020). "We observed that BPA induced hypermethylation of TIMP3, CHFR, ESR1, and IGSF4 while HBCD induced TIMP3 tumor suppressor gene hypermethylation in MCF7 breast cancer cell line." (PMID 32466334, 2020). "In order to investigate this detected mRNA expression, we compared the ERBB2, ESR1, and PGR mRNA expression in available TCGA breast cancer samples and grouped the expression values by the annotated result of the immunohistochemistry (IHC) assay." (PMID 32793490, 2020). "Using TENET, biomarkers and potential oncogenic drivers of breast cancer (e.g. GATA3, ESR1, FOXA1), prostate cancer (e.g. FOXA1, HOXC6, HOXB13), and kidney cancer (e.g. GLIS1, MAF, RUNX1) have been identified." (PMID 32925947, 2020). "Along with ESR-1; EGFR, MET, and VEGFR are located centrally in the network which indicates the role of proteins in the pathogenesis of breast cancer." (PMID 33057155, 2020). "This comprehensive dataset included many established biomarkers for breast cancer, including the receptor tyrosine kinase erbB-2 (HER2), estrogen receptor (ESR1), progesterone receptor (PGR), and androgen receptor (AR)." (PMID 32489334, 2020). "In the previous step, we performed a single gene characterization of the hub gene related to the overall survival rate of breast cancer, and we found that all PTGS2, ESR1, and FOS were enriched in the PPAR signaling pathway." (PMID 33149754, 2020). "Most previous studies reported estrogen receptors as a prognostic marker for hormone‐related tumors, such as ESR1 in thyroid carcinoma, and ESR1 and ESR2 in ovarian and breast cancer." (PMID 32536040, 2020). "BPA induced hypermethylation of TIMP3, CHFR, ESR1, and IGSF4 while HBCD induced TIMP3 tumor suppressor gene hypermethylation in MCF7 breast cancer cell line." (PMID 32466334, 2020). "We previously reported that a cluster of ncRNAs, named Eleanors, is transcribed from a 0.7-Mb region containing the ESR1 gene (chr6:152083078-152424447, hg19) in LTED cells derived from human breast cancer MCF7 cells." (PMID 32047236, 2020). "Here, we present a list of seven putative genes that are modulated by Rsv in breast cancer in the context of cotreatment with Doxo: HSP90AA1, CCND1, CDH1, ESR1, MAPK3, PTPN11, and RPS6KB1." (PMID 33204396, 2020). "Next, we compared the BRF2 Outlier results to known breast cancer biomarkers, HER2 (ERBB2), MYC, PIK3CA, and ER (ESR1) using the same stringent threshold criterion." (PMID 33176745, 2020). "However, detailed functional characterization and evidence demonstrating a causal role for ESR1 fusions in endocrine therapy resistance has been lacking and the incidence of ESR1 fusions from late-stage ER+ breast cancer still remains unclear." (PMID 31106278, 2019). "As previously shown in breast cancer, DOT1L inhibition resulted in a dose-dependent inhibition of ESR1 gene expression in both cell lines, as demonstrated by a decrease of both ERα mRNA and protein levels upon EPZ treatment." (PMID 31689915, 2019).